LNP1 (leukemia NUP98 fusion partner 1)
Synonyms: NP3
Tractability: No criterion of Open Targets' tractability assessment is met for any kind of drug.
Gene: Protein-coding gene on chromosome 3 (100,401,192 to 100,457,563, forward strand). Ensembl gene ENSG00000206535.
Subcellular location (Human Protein Atlas): Vesicles; Cytosol; Nuclear speckles
Genetic constraint (gnomAD): Loss-of-function variants: 12 observed, 14.41 expected, observed/expected ratio (o/e) 0.83, 90% interval 0.53 to 1.35. The upper end of that interval is the gene's LOEUF score, 1.35, which puts it in group 5 of 6, group 1 being the genes least tolerant of losing a copy. Missense variants: 193 observed, 215.9 expected, observed/expected ratio (o/e) 0.89, 90% interval 0.79 to 1.01. Synonymous variants: 75 observed, 76.19 expected, observed/expected ratio (o/e) 0.98, 90% interval 0.82 to 1.19.
Homologues: Orthologues: chimpanzee LNP1 (99% identical), macaque LNP1 (98% identical), rabbit LNP1 (80% identical), dog LNP1 (77% identical), pig LNP1 (76% identical), rat Lnp1 (63% identical), mouse Lnp1 (62% identical).
Diseases named in the same sentence as LNP1 in open-access papers:
LNP1 is named in the same sentence as 24 diseases in open-access papers, as found by Europe PMC text mining. Sharing a sentence is not in itself a finding about the gene and the disease. The quoted sentences say what the papers report.
leukemia (2 papers, 2024 to 2025). A malignant (clonal) hematologic disorder, involving hematopoietic stem cells and characterized by the presence of primitive or atypical myeloid or lymphoid cells in the bone marrow and the blood. "LNP1 is known to fuse with NUP98 in genome rearrangements of leukemia patients while the 14-3-3 complex is involved with many signaling pathways and associated with cancer." (PMID 39464102, 2024).
malaria (2 papers, 2021 to 2022). Malaria is a serious and sometimes fatal disease caused by a parasite that commonly infects a certain type of mosquito which feeds on humans. "Based on humoral and cytokine responses, only LNP1 advanced to more comprehensive analyses including protection studies in rodent malaria models." (PMID 34145286, 2021).
autism (1 paper, 2025). Persistent deficits in social interaction and communication and interaction as well as a markedly restricted repertoire of activity and interest as well as repetitive patterns of behavior. "Several of these functionally uncharacterized proteins are associated with human diseases including ciliary dyskinesia (CLXN), Lui-Jee-Baron syndrome (SPIN4), lymphoblastic leukemia (LNP1, SLX4IP), lethal skeletal dysplasia (TMEM263), and association to autism and fragile X syndrome (DIPK2B)." (PMID 40425816, 2025).
lymphoma (1 paper, 2018). A malignant (clonal) proliferation of B- lymphocytes or T- lymphocytes which involves the lymph nodes, bone marrow and/or extranodal sites. "LNP1—together with other highly mutated genes, such as FADS6 and TRAK1—was firstly found in this lymphoma, and was verified by Sanger sequencing." (PMID 30106962, 2018).
melanoma (1 paper, 2020). A malignant, usually aggressive tumor composed of atypical, neoplastic melanocytes. "First of all, we exposed melanoma cells for 72 h to LNP1 (empty), LNP2 (carrying miR-204-5p), LNP3 (carrying miR-199b-5p) or LNP4 (with both therapeutic oncosuppressor miRNAs) to determine their proliferation through crystal violet staining." (PMID 32178301, 2020). "Again, we exposed A375 and M14 melanoma cells to LNP1 or LNP4 for 72 h." (PMID 32178301, 2020). "Finally, in order to exclude that LNPs growth inhibitory effects is due to the nanoparticles themselves and not to their therapeutic cargo, we exposed melanoma cells to control LNP1." (PMID 32178301, 2020).
cancer (3 papers, 2023 to 2025). A tumor composed of atypical neoplastic, often pleomorphic cells that invade other tissues. "The significant downregulation of Lnp1, a fusion partner of NUP98 associated with hematopoietic malignancies, underscores the potential cancer-related implications of FAE, aligning with results from other studies that have linked folate metabolism to increased cancer risk." (PMID 41509541, 2025).
infection (3 papers, 2021 to 2024). The state of being infected such as from the introduction of a foreign agent such as serum, vaccine, antigenic substance or organism. "Collectively, the data clearly indicate that vaccination with either the LNP1 or LNP2 vaccine fully protected pigs against challenge infection with the homologous IAV-S strain." (PMID 37896997, 2023). "Thus, the LNP1 vaccine may elicit a different T-cell response compared to the LNP2 vaccine, but it remains unclear how much such a difference in the T-cell response contributes to the protection of pigs against challenge infection." (PMID 37896997, 2023).
LNP1 also shares sentences with these, for which no sentence is quoted: acute leukemia (1 paper); allergic asthma (1); asthma (1); bacterial infection (1); breast carcinoma (1); bronchopneumonia (1); ciliary dyskinesia (1); COVID-19 (1); fragile X syndrome (1); head and neck squamous cell carcinoma (1); infection of the skin (1); Lethal skeletal dysplasia (1); Lui-Jee-Baron syndrome (1); lymphoblastic leukemia (1); Obesity (1); Stroke (1); tumour (1).